NR2F2 (nuclear receptor subfamily 2 group F member 2)
Description:
Ligand-activated transcription factor. Activated by high concentrations of 9-cis-retinoic acid and all-trans-retinoic acid, but not by dexamethasone, cortisol or progesterone (in vitro). Regulation of the apolipoprotein A-I gene transcription. Binds to DNA site A. May be required to establish ovary identity during early gonad development.
Synonyms: ARP-1; ARP1; TFCOUP2; COUP-TFII; COUPTFB; SVP40; NF-E3; COUPTF2; CHTD4; COUPTFII; SRXX5
Tractability: Small molecule: it belongs to a druggable protein family. PROTAC: ubiquitination databases record sites on it; a small molecule that binds it is known.
Target class: Nuclear hormone receptor subfamily 2 group F member 2; Transcription factor; Nuclear receptor; Nuclear hormone receptor subfamily 2; Nuclear hormone receptor subfamily 2 group F
Safety:
Unwanted effects reported when the protein is acted on. In parentheses: how it was acted on, where the effect was seen, and who reports it.
Decreased sperm quantity / quality in the adult, Decreased fertility (inhibition; source: AOP-Wiki)
Decreased fertility in the adult, Decreased sperm quantity and/or quality in the adult testis (inhibition; source: AOP-Wiki)
Gene: Protein-coding gene on chromosome 15 (96,325,797 to 96,340,263, forward strand). Ensembl gene ENSG00000185551.
Subcellular location: Nucleus
Subcellular location (Human Protein Atlas): Nucleoplasm; Cytosol
Pathways (Reactome):
Chromatin organization: Interaction of NuRD complexes with transcription factors
Developmental Biology: Transcriptional regulation of white adipocyte differentiation
Gene Ontology:
Molecular function: DNA-binding transcription factor activity; DNA-binding transcription repressor activity, RNA polymerase II-specific; nuclear receptor activity; protein binding; protein homodimerization activity; retinoic acid binding; sequence-specific DNA binding; RNA polymerase II cis-regulatory region sequence-specific DNA binding; DNA binding; zinc ion binding
Biological process: female gonad development; lymphatic endothelial cell fate commitment; negative regulation of endothelial cell migration; negative regulation of endothelial cell proliferation; negative regulation of transcription by RNA polymerase II; negative regulation of vascular endothelial growth factor signaling pathway; positive regulation of DNA-templated transcription; positive regulation of transcription by RNA polymerase II; cell differentiation; nervous system development; regulation of transcription by RNA polymerase II; intracellular receptor signaling pathway; lymph vessel development; positive regulation of systemic arterial blood pressure; regulation of DNA-templated transcription; response to estradiol
Cellular component: nucleus; nucleoplasm
Genetic constraint (gnomAD): Loss-of-function variants: 2 observed, 31.97 expected, observed/expected ratio (o/e) 0.0626, 90% interval 0.025 to 0.2. The upper end of that interval is the gene's LOEUF score, 0.2, which puts it in group 1 of 6, group 1 being the genes least tolerant of losing a copy. Missense variants: 300 observed, 576.58 expected, observed/expected ratio (o/e) 0.52, 90% interval 0.47 to 0.57. Synonymous variants: 274 observed, 251.48 expected, observed/expected ratio (o/e) 1.09, 90% interval 0.99 to 1.2.
Homologues: Orthologues: chimpanzee NR2F2 (100% identical), macaque NR2F2 (100% identical), mouse Nr2f2 (100% identical), guinea pig NR2F2 (99% identical), pig NR2F2 (99% identical), rat Nr2f2 (99% identical), tropical clawed frog nr2f2 (93% identical), zebrafish nr2f2 (88% identical), rabbit NR2F2 (67% identical), Drosophila melanogaster usp (33% identical), Caenorhabditis elegans nhr-41 (32% identical), Drosophila melanogaster Hr78 (30% identical), and 24 more. Paralogues in human: NR2F1 (87% identical), NR2F6 (61% identical), RXRA (40% identical), RXRB (38% identical), RXRG (38% identical), NR2C2 (37% identical), NR2E3 (37% identical), NR2C1 (34% identical), HNF4A (33% identical), HNF4G (33% identical), NR2E1 (32% identical).
Diseases named in the same sentence as NR2F2 in open-access papers:
NR2F2 is named in the same sentence as 135 diseases in open-access papers, as found by Europe PMC text mining. Sharing a sentence is not in itself a finding about the gene and the disease. The quoted sentences say what the papers report.
breast cancer (30 papers, 2010 to 2026). A primary or metastatic malignant neoplasm involving the breast. "Higher expression of NR2F2 was associated with a worse prognosis and lymph node metastasis in human breast cancer cases." (PMID 32631390, 2020). "In Luminal A breast cancer, high NR2F2 expression is associated with improved patient survival." (PMID 41328346, 2026). "Nuclear receptor subfamily 2, group F, member 2 (NR2F2) has been implicated in the development of breast cancer, however its contribution to insulin-induced EMT in breast cancer remains unclear." (PMID 32631390, 2020). "In order to identify that whether EMT induced by insulin in breast cancer cells is mediated by NR2F2, we performed loss of function experiments in our in vitro model." (PMID 32631390, 2020). "NR2F2 has also been associated with estrogen receptor alpha (ERα) signaling and may influence hormone responsivity in breast cancer." (PMID 22829776, 2012). "Next, using publicly available binding site data of ERα-associated TFs, we show that the identified core sites bound by FOXC1 in TNBC are bound by FOXA1 and NR2F2 in ER+ breast cancer." (PMID 39171293, 2024). "NR2F2 played a key role in the proliferation and invasion of gastric and breast cancer cells through its effect on MET." (PMID 36172369, 2022). "We observed that the top five strongest TF co-occupancy pairs associated with breast cancer risk were FOXA1 + E2F1, FOXA1 + NR2F2, FOXA1 + ESR1, FOXA1 + SIN3, and FOXA1 + TCF12." (PMID 34518541, 2021). "All these findings suggested that NR2F2 has an important role in ER-positive luminal A type breast cancer." (PMID 32168782, 2020). "There is increasing evidence that NR2F2 plays some kind of a role in the progression of breast cancer." (PMID 32168782, 2020). "Our results showed that high NR2F2 expression is correlated with better survival in luminal A breast cancer patients only." (PMID 32168782, 2020). "Our results suggest that insulin promotes breast cancer cell invasion, migration by upregulating expression of NR2F2, which plays a critical role in insulin-mediated breast cancer cell invasion, migration through its effect on EMT." (PMID 32631390, 2020). "To examine the expression of the NR2F2 gene in different breast cancer subgroups, we used the RNA-Seq data of 817 patients derived from a TCGA database." (PMID 32168782, 2020). "We have found that patients with luminal A breast cancer and a high expression of NR2F2 have better disease-free survival (logrank p < 0.0001, Mantel-Cox test) than those with a low NR2F2 level." (PMID 32168782, 2020). "In the process of the transcriptome profiling of NR2F2-depleted breast cancer cells such differentially expressed genes have been identified that are involved in endocrine therapy resistance and are also ERα target genes." (PMID 32168782, 2020). "To examine the regulation of gene expression by NR2F2 in luminal A breast cancer cells, we depleted NR2F2 using the lentiviral shRNA approach and then performed mRNA sequencing." (PMID 32168782, 2020). "Overall, these findings demonstrate that the NR2F2 nuclear receptor has a key role in ERα-mediated transcription and it can offer a potential therapeutic target in patients with luminal A breast cancer." (PMID 32168782, 2020). "Here, we examined the regulatory mechanisms by NR2F2 in luminal A breast cancer cells on the genome level to investigate its role in the ERα regulatory complex." (PMID 32168782, 2020). "Overall, these findings confirm the role of NR2F2 in ERα-mediated transcriptional regulations in breast cancer cells with luminal A subtype." (PMID 32168782, 2020). "It has been shown in breast cancer that the expression of the NR2F2 is lower in ER-negative cancer and it participates in chemoresistance in cell-type and agent-specific form." (PMID 32168782, 2020). "In our paper, we demonstrated that breast cancer patients with the luminal A subtype who have a high NR2F2 expression show better survival." (PMID 32168782, 2020).
breast cancer (continued). "To investigate the effect of NR2F2 on gene expression, we performed RNA-Seq from NR2F2-depleted breast cancer cells." (PMID 32168782, 2020). "In this paper, we investigated the gene expression level of NR2F2 in patients with different breast cancer subtypes." (PMID 32168782, 2020). "We found that NR2F2 played a crucial role in insulin-mediated EMT in breast cancer cells by increasing vimentin and N-cadherin and inhibiting E-cadherin levels." (PMID 32631390, 2020). "In the current study, we studied the effect of NR2F2 on insulin-mediated EMT in the breast cancer cells lines, MDA-MB-231 and MCF-7." (PMID 32631390, 2020). "A recent study support these observations by noting that EGF-mediated MAPK signaling pathway significantly induced NR2F2 expression in human breast cancer cell lines." (PMID 32631390, 2020). "Immunofluorescence assays against NR2F2 in MCF-7 breast cancer cells deprived of oestrogen further demonstrated its localization to the nucleus." (PMID 31588232, 2019). "IHC staining of NR2F2 in breast cancer primary biopsy tissue with metastatic lymph nodes demonstrated that a reduction in COUP-TFII was associated with an increased tumour stage and worse progression of malignancy in breast cancer." (PMID 31588232, 2019). "Nuclear receptor subfamily 2 (NR2F2,as known as COUP-TFII) is found in many cancers, including breast cancer, ovarian cancer and colorectal cancer." (PMID 27844448, 2017). "NR2F2 has been also detected up-regulated in breast cancer, but its involvement in tumor development remains elusive because of its ability to affect both pro-oncogenic and anti-oncogenic proteins." (PMID 21209903, 2010). "Several of these genes have been linked to breast cancer (MAPT, HMGCS2, NR2F2, TFAP2B, NTN4, SEC14L2 and LTF)." (PMID 21209903, 2010). "Finally, we show that core FOXC1 targets in TNBC are regulated in parallel by the pioneer factor FOXA1 and the nuclear receptor NR2F2 in ER + breast cancer." (PMID 39171293, 2024). "NR2F2 acts as an oncogene in other cancers, such as renal, prostate, or breast cancers." (PMID 37445988, 2023). "Our findings suggest the importance of NR2F2 in breast cancer treatment and prognosis." (PMID 32168782, 2020). "Our results suggest that NR2F2 may play an important role in the survival and treatment of breast cancer patients with an ER-positive subtype." (PMID 32168782, 2020). "We sought to identify whether NR2F2 is a regulator of EMT in breast cancer cells and compared NR2F2 expression between MDA-MB-231 and MCF-7 cells." (PMID 32631390, 2020). "To understand the molecular mechanism of NR2F2 in breast cancer, we determined the cistrome and transcriptome of NR2F2 in the ER-positive breast cancer cell lines (MCF-7 and T47D) using the chromatin immunoprecipitation followed by high-throughput sequencing (ChIP-seq) and RNA-seq methods." (PMID 32168782, 2020). "In our study, we performed NR2F2 and ERα ChIP-Seq from luminal A breast cancer cell lines." (PMID 32168782, 2020). "However, Zhang has found the opposite, claiming that the high expression of NR2F2 shows better overall and disease-free survival in breast cancer patients." (PMID 32168782, 2020). "Yet, the expression of NR2F2 has an inverse correlation with tumor grade in breast cancer." (PMID 32631390, 2020). "Several studies have reported that NR2F2 is a critical nuclear receptor in cardiovascular development, but we demonstrate that this nuclear receptor has a different molecular function in breast cancer." (PMID 32168782, 2020). "In our paper, we demonstrated the presence of NR2F2 in regulation by ERα in breast cancer cells." (PMID 32168782, 2020). "All these suggest that NR2F2 promotes EMT of breast cancer cells." (PMID 32631390, 2020). "This further confirmed the effect of NR2F2 on EMT in breast cancer cells." (PMID 32631390, 2020).
breast cancer (continued). "Finally, the transcriptome profiling of NR2F2 depleted ER-positive breast cancer cells showed that NR2F2 plays a role in the expression of genes regulating cell cycle and that of estrogen responsive genes." (PMID 32168782, 2020). "Overall, these results demonstrate that NR2F2 is required for efficient transcription of ERα target genes and support a functional role for NR2F2 in mediating oestrogen-dependent cell growth in ER positive breast cancer cell lines." (PMID 31588232, 2019). "Furthermore, to measure the effects of NR2F2 knockdown on proliferation of other breast cancer cells lines, we chose another two ER positive cell lines BT-474 and T-47D to perform MTT assay." (PMID 31588232, 2019). "Taken together the available results indicate that NR2F1 and NR2F2 are characterized by onco-suppressive properties in breast cancer, suggesting that strategies aimed at increasing their expression levels or aimed at stimulating their transcriptional activity are likely to be of therapeutic value." (PMID 26894976, 2016). "For breast cancer, we report enrichment for ESR1 DNA bindings in gained enhancer loci in MCF-7 cell line relative to MCF-10A cell line, as well as NR2F2 which encodes a member of the steroid thyroid hormone receptor, involved in apoptosis and increased proliferation." (PMID 25477382, 2015). "NR2F2 hypermethylation has recently been described in breast carcinomas and AML." (PMID 21603610, 2011). "Whether NR2F2 and FOXC1 influence their respective binding in TNBC remains to be determined, but the possibility of using the NR2F2-inhibitor to disrupt the interaction with FOXC1 in TNBC presents a potential targeted-therapy approach for basal-like breast cancer." (PMID 39171293, 2024). "However, there is limited knowledge about the cistrome and transcriptome of NR2F2 in breast cancer." (PMID 32168782, 2020). "To investigate the cistrome of NR2F2 and its presence in the ERα-mediated transcriptional complex, we performed chromatin immunoprecipitation followed by sequencing (ChIP-seq) with NR2F2 and ERα antibodies using two luminal A breast cancer cells (MCF-7 and T47D)." (PMID 32168782, 2020). "Our results suggest that NR2F2 may play an important role in breast cancer metastasis and thus may be a potential drug target to prevent metastasis in breast cancer with hyperinsulinemia patients or breast cancer with type 2 diabetes patients." (PMID 32631390, 2020). "Thus, NR2F2 inhibits the TGF-β-dependent epithelial-mesenchymal transition in breast cancer." (PMID 31588232, 2019). "Among breast cancer subtypes, its expression is highest in the luminal A subtype; although in the TNBC cell lines Bt549 and MDA-MB-231 used in this study, NR2F2 expression is comparable to that in MCF-7, a luminal A cell line." (PMID 39171293, 2024). "NR2F2 is an orphan nuclear receptor in the steroid hormone receptor family that influences cell invasion, migration and EMT in breast cancer." (PMID 39171293, 2024). "Several transcriptional corepressors are involved in breast cancer, but nuclear corepressors (NCOR1), NCOR2, and the nuclear receptor subfamily 2, group F, member 2 (NR2F2) are the best-characterized corepressors." (PMID 33841325, 2021). "We demonstrate that NR2F2 promotes EMT of breast cancer cell lines, resulting in enhanced breast cancer cells migration and invasion in vitro." (PMID 32631390, 2020). "The concurrent expression of GATA3, NR2F2, and FOXA1 in ERα positive breast carcinomas is intriguing." (PMID 31588232, 2019). "Relative to the normal gland, mammary-tumors contain smaller and equal amounts of NR2F1 and NR2F2, respectively." (PMID 26894976, 2016). "Numerous studies have examined the role of NR2F2 in breast cancer cells and patients; however, its function has still not been clarified." (PMID 32168782, 2020). "We found that insulin upregulated NR2F2 expression in MCF-7 and MDA-MB-231 breast cancer cells." (PMID 32631390, 2020).
breast cancer (continued). "In summary, along with the observation that FOXC1 and NR2F2 co-interact, it is likely that core binding sites of FOXC1 in TNBC identified here and represented by cluster 1 and cluster 4 peaks, are sites where FOXA1/NR2F2 are bound in luminal breast cancer (and vice versa)." (PMID 39171293, 2024). "All this supports that NR2F2 plays an important role in the response given to the treatment of breast cancer patients; however, the genome-wide regulation of NR2F2 is not known in breast cancer." (PMID 32168782, 2020).
prostate carcinoma (19 papers, 2014 to 2026). A carcinoma that arises from epithelial cells of the prostate gland. "This prevents NR2F2 from regulating downstream target genes and has been shown to effectively inhibit prostate cancer growth." (PMID 41328346, 2026). "NR2F2 (COUP-TFII) plays a critical role in mediating the effects of DHA treatment on EFNB2, EBF1, ETS1, and VEGFA expression, and the knockdown of NR2F2 can recede the functional changes induced by DHA treatment in prostate cancer cells." (PMID 39364872, 2025). "NR2F2 serves as both a prognostic marker and a therapeutic target for prostate cancer, with alterations in its expression influencing therapeutic resistance mechanisms." (PMID 39364872, 2025). "Targeting NR2F2 with small-molecule drugs shows promise for therapeutic effects in prostate cancer treatment." (PMID 39364872, 2025). "A small molecule inhibitor of NR2F2 was recently shown to reduce prostate cancer tumor growth, specifically by interrupting the interaction of NR2F2 with FOXA1, a master regulator in prostate tumorigenesis." (PMID 39171293, 2024). "Our study suggests that DHA treatment affects the functions of DU145 and PC-3 cells by regulating the expression of NR2F2 and its potential target genes, and NR2F2 may serve as a potential therapeutic target for prostate cancer." (PMID 39364872, 2025). "Recent evidence suggests that inhibition of Nr2f2 with a small molecular compound could suppress the progression and metastasis of prostate cancer, which reflects the application prospect of targeting Nr2f2." (PMID 36081650, 2022). "COUP-TFII (NR2F2), an ONR of the highly conserved NR2F subfamily, displays an increased expression pattern in advanced prostate cancer, and its expression is positively correlated with prostate tumor recurrence and progression." (PMID 33750894, 2021).
congenital heart disease (8 papers, 2014 to 2025). A heart disease that is present at birth. "Pathogenic variants in NR2F2 have been associated with congenital malformations, including congenital heart disease, congenital diaphragmatic hernia, and syndromic 46,XX testicular or ovo-testicular difference/disorder in sex development (DSD)." (PMID 40637239, 2025). "To date, 35 different variants have been described in NR2F2, and the majority of these are related to congenital heart defects." (PMID 38812815, 2024). "Compatible with the expression pattern of NR2F2, congenital heart defects are the well-known phenotypes associated with the variants of this gene." (PMID 38812815, 2024). "De novo heterozygous NR2F2 frameshift variants cause testicular development in 46, XX patients born with atypical male external genitalia, congenital heart disease (CHD) and other somatic features." (PMID 36110220, 2022). "NR2F2 is a ligand inducible transcription factor that is involved in the regulation of many different genes and the deletion of NR2F2 was considered to possibly contribute to congenital heart defects." (PMID 24479926, 2014).